TMEM170A (transmembrane protein 170A)
Description:
Acts as a regulator of endoplasmic reticulum (ER) and nuclear envelope (NE) morphogenesis. Affects the ratio between tubular ER and ER sheets by promoting sheet formation at the expense of tubules. Influences NE expansion, nuclear pore complex formation and proper localization of inner nuclear membrane proteins.
Synonyms: TMEM170; FLJ37611
Tractability: Antibody: UniProt predicts a signal peptide or a membrane-spanning region. PROTAC: ubiquitination databases record sites on it.
Gene: Protein-coding gene on chromosome 16 (75,443,054 to 75,465,497, reverse strand). Ensembl gene ENSG00000166822.
Subcellular location: Endoplasmic reticulum membrane; Nucleus envelope
Gene Ontology:
Molecular function: protein binding
Biological process: endoplasmic reticulum tubular network organization; nuclear envelope organization; nuclear pore complex assembly
Cellular component: endoplasmic reticulum membrane; nuclear envelope
Genetic constraint (gnomAD): Loss-of-function variants: 18 observed, 12.35 expected, observed/expected ratio (o/e) 1.46, 90% interval 0.99 to 1.91. The synonymous counts are far from expectation, so gnomAD's model fits this gene poorly and the ratio says little. Missense variants: 220 observed, 181.91 expected, observed/expected ratio (o/e) 1.21, 90% interval 1.08 to 1.35. Synonymous variants: 107 observed, 75.9 expected, observed/expected ratio (o/e) 1.41, 90% interval 1.2 to 1.65.
Homologues: Orthologues: pig TMEM170A (97% identical), mouse Tmem170 (96% identical), tropical clawed frog tmem170a (85% identical), chimpanzee TMEM170A (83% identical), guinea pig TMEM170A (81% identical), dog TMEM170A (67% identical), rabbit TMEM170A (67% identical), zebrafish tmem170a (60% identical), Drosophila melanogaster CG12341 (42% identical), Caenorhabditis elegans F43G9.13 (28% identical). Paralogues in human: TMEM170B (44% identical).
Diseases named in the same sentence as TMEM170A in open-access papers:
TMEM170A is named in the same sentence as 9 diseases in open-access papers, as found by Europe PMC text mining. Sharing a sentence is not in itself a finding about the gene and the disease. The quoted sentences say what the papers report.
autoimmune disease (1 paper, 2020). A disorder resulting from loss of function or tissue destruction of an organ or multiple organs, arising from humoral or cellular immune responses of the individual to their own tissue constituents. "Three AMD-associated genes (BCAR1, CFDP1, and TMEM170A) residing within a locus on chromosome 16 (chr16:75233867-75516739), coincide with GWAS signals of six different trait groups, namely “organ function”, “cancer”, “neurological diseases”, “autoimmune diseases”, “metabolic traits”, and “AMD”." (PMID 32005911, 2020).
breast carcinoma (1 paper, 2023). "It is located at the reverse strand of chromosome 16 and consists of seven exons, which encode for a protein product of 299 aa, and it is flanked by the BCAR1 (breast cancer antiestrogen resistance 1) and TMEM170A (transmembrane protein 170A) genes." (PMID 37566073, 2023).
Headache (1 paper, 2022). Cephalgia, or pain sensed in various parts of the head, not confined to the area of distribution of any nerve. "Cross-trait gene-based overlap analysis identified 33 genes significantly associated (Pgene-based < 3.85 × 10−6) with migraine and T2D, and 11 genes associated with headache and T2D, with 7 genes (EHMT2, SLC44A4, PLEKHA1, CFDP1, TMEM170A, CHST6, and BCAR1) common between them." (PMID 36292730, 2022). "Notably, seven of these genes (EHMT2, SLC44A4, PLEKHA1, CFDP1, TMEM170A, CHST6, and BCAR1) were genome-wide significant for all three traits (migraine, headache, and T2D)." (PMID 36292730, 2022).
cancer (3 papers, 2020 to 2022). A tumor composed of atypical neoplastic, often pleomorphic cells that invade other tissues. "The duplication encompasses 6 genes four of which are frequently deregulated in cancer (TMEM170A, CHST6, CHST5, TMEM231)." (PMID 35221838, 2022).
TMEM170A also shares sentences with these, for which no sentence is quoted: aortic stenosis (1 paper); coronary artery disease (1); migraine (1); neurological diseases (1); tumor (1).